WT1 (WT1 transcription factor)
Diseases named in the same sentence as WT1 in open-access papers (continued):
Sharing a sentence is not in itself a finding about the gene and the disease.
pilocytic astrocytoma (2 papers, 2018 to 2020). Pilocytic astrocytoma is a rare subtype of low-grade glioma of the central nervous system characterized by a well circumscribed, often cystic, brain tumor with a discrete mural nodule and long, hair-like projections that extend from the neoplastic astrocytes. "A percentage of pilocytic astrocytomas has a high WT1 score that associates increased Bcl2 and Ki67 indices." (PMID 32856872, 2020). "In spite of being low-grade tumors, an unexpectedly higher WT1 expression (either in frequency or score) was described in pilocytic astrocytomas and SEGA as compared to grade II diffuse astrocytomas in different studies." (PMID 32856872, 2020). "In a striking disparity, 21.4% of our pilocytic astrocytomas and 75% of SEGAs revealed a +3 WT1 staining and virtually all SEGAs were WT1 positive." (PMID 32856872, 2020). "A considerable percentage (21.4%) of pilocytic astrocytomas revealed a WT1+3 staining." (PMID 32856872, 2020).
retinoblastoma (2 papers, 2007 to 2024). A malignant tumor that originates in the nuclear layer of the retina. "Some of them are reported to share the same oncogenes, as WT1 in Wilms' tumour, in retinoblastoma and in acute myeloid leukaemia, and RB1 in retinoblastoma, neuroblastoma, childhood leukaemia and Ewing's sarcoma." (PMID 17595660, 2007).
salivary gland cancer (2 papers, 2013 to 2020). A primary or metastatic malignant neoplasm that affects the major or minor salivary glands. "Conversely, in patient No.4 with salivary gland cancer, the immunological responses failed as negative following to the criteria of immune monitoring for WT1-CTLs." (PMID 32231023, 2020).
sarcomatoid mesothelioma (2 papers, 2017 to 2024). A diffuse malignant mesothelioma arising from the pleura and less often the peritoneum. "Namely, by using a combination of Wilms' tumour 1 (WT1) protein, CAM5.2, and AE1/3 cytokeratins, it is possible to distinguish between sarcomatoid carcinoma and sarcomatoid mesothelioma with a specificity of 97.7%." (PMID 38459714, 2024). "Sarcomatoid mesotheliomas are CKMNF116 (cytokeratines 5, 6, 8, 17, and 19) and WT-1 positive." (PMID 28358042, 2017).
Splenomegaly (2 papers, 2018 to 2020). Abnormal increased size of the spleen. "Wt1+/R394W mice have mild splenomegaly compared to wild type mice (spleen weights, 0.11 ± 0.005 g vs. 0.09 ± 0.007 g for wild type, p = 0.049), but there were no appreciable differences in the peripheral blood counts between 2-month old wild type and Wt1+/R394W littermates." (PMID 30450160, 2018).
teratoma (2 papers, 2015 to 2016). A non-seminomatous germ cell tumor characterized by the presence of various tissues which correspond to the different germinal layers (endoderm, mesoderm, and ectoderm). "A picture emerges where the WT1-mutant tumours start as a purely developmental problem, almost like a teratoma that is restricted to the mesodermal lineage, whereas the WT1-wild-type tumours are more classical cancers right from the start." (PMID 26035382, 2015).
thrombotic microangiopathy (2 papers, 2017 to 2025). The syndromes of microangiopathic hemolytic anemia, thrombocytopenia, and variable signs of organ impairment, due to platelet aggregation in the microcirculation. "This case is distinctive due to its unusual onset, the presence of thrombotic microangiopathy (TMA), and the detection of a heterozygous missense mutation in the WT1 gene (c.1298G>A, p.Cys433Tyr) located in exon 8, in association with a 46 XY karyotype." (PMID 40426774, 2025).
thyroid cancer (2 papers, 2018 to 2022). "Then, we confirmed that higher WT1 levels were closely related to worse prognosis in thyroid cancer patients with BRAF mutation." (PMID 35123502, 2022). "Sankey plot indicated the relationship between TNM stage, BRAF mutated status and WT1 expression in thyroid cancer patients." (PMID 35123502, 2022). "However, The KM plot showed higher expression level of WT1 predicted worse overall survival time in thyroid cancer patients carrying BRAF mutation." (PMID 35123502, 2022). "Then, TNM stage and WT1 expression levels were used to construct a predictive nomogram of thyroid cancer patients in the TCGA-THCA cohort." (PMID 35123502, 2022). "Next, the prognotic role of WT1 was assessing between BRAF mutated and BRAF wild-type thyroid cancer patients." (PMID 35123502, 2022). "The results revealed that TNM stage and WT1 expression levels can be regarded as independent prognostic factors in thyroid cancer patients in the TCGA-THCA cohort." (PMID 35123502, 2022). "The expression level of WT1 is remarkably increased in primary thyroid cancer, and WT1 is regarded as a critical prognostic biomarker related to recurrence-free survival in thyroid cancer patients." (PMID 35123502, 2022). "The results showed that WT1 is a significantly important regulator in thyroid cancer patients." (PMID 35123502, 2022). "Then, we confirmed the prognostic role of WT1 in thyroid cancer patients." (PMID 35123502, 2022). "Interestingly, WT1 was also upregulated in thyroid cancer samples with mutant BRAF compared with thyroid cancer samples with wild-type BRAF." (PMID 35123502, 2022). "In addition, higher WT1 expression predicted worse survival time in thyroid cancer patients, and the AUC of the ROC curve reached 0.8, 0.8, 0.66 and 0.69 at 1 year, 2 years, 4 years and 8 years, respectively, indicating a superior predictive performance of WT1 for thyroid cancer patients." (PMID 35123502, 2022). "Interestingly, A GSEA indicated that WT1 is involved in the “MAPK signaling pathway” and “mTOR signaling pathway” in thyroid cancer patients." (PMID 35123502, 2022). "There was no significant change in survival time compared with high WT1 expression and low WT1 expression in BRAF wild-type thyroid cancer patients." (PMID 35123502, 2022).
triple-negative breast carcinoma (2 papers, 2018 to 2024). An invasive breast carcinoma which is negative for expression of estrogen receptor (ER), progesterone receptor (PR), and human epidermal growth factor receptor 2 (HER2). "However, in a sub-group of carcinomas with a particularly poor prognosis—triple-negative breast cancers—WT1 expression levels were significantly higher than in control tissue." (PMID 30374123, 2018).
tuberculosis (2 papers, 2015 to 2023). A chronic, recurrent infection caused by the bacterium Mycobacterium tuberculosis. "Two genome-wide significant results were recorded for tuberculosis, belonging to WT1 gene and ASAP1 gene." (PMID 26524966, 2015). "In addition, WT1 gene from GWAS studies, implied in susceptibility to tuberculosis, has been described to be under control of CCL2, which seems to be having target-responsive cytocidal activity on WT1-specific mechanisms." (PMID 26524966, 2015). "This could be part of the larger pathway that explains the relationship between tuberculosis and carcinogenesis involving the CCL7-CCL2-CCR2 axis, which has a role in the immune response, tumor regulation and the WT1 gene associated with the susceptibility to tuberculosis." (PMID 37108169, 2023).
Ureteral obstruction (2 papers, 2013 to 2023). Obstruction of the flow of urine through the ureter. "Nitric oxide bioavailability associated with Hsp70 interaction may modulate wt-1 mRNA expression, preventing obstruction-induced cell death during neonatal unilateral ureteral obstruction." (PMID 24288526, 2013). "We also observed WT1 expression in PTECs in unilateral ureteral obstruction or cisplatin-induced AKI mice models." (PMID 36923529, 2023). "Of great interest, nitric oxide bioavailability associated with heat shock protein 70 (Hsp70) interaction may modulate wt-1 mRNA expression, preventing obstruction-induced cell death during neonatal unilateral ureteral obstruction." (PMID 24288526, 2013).
AIDS (1 paper, 2024). A syndrome resulting from the acquired deficiency of cellular immunity caused by the human immunodeficiency virus (HIV). "KS tumor biopsies from 294 PLWH and advanced stage AIDS-Kaposi sarcoma in a multinational clinical trial (ACTG A5263/AMC 066; NCT01435018) were sectioned for H&E, and immunohistochemistry (IHC) for WT1 and LANA was performed." (PMID 38190392, 2024).
ameloblastoma (1 paper, 2022). The most common odontogenic tumor, arising from the epithelial component of the embryonic tooth and usually affecting the molar-ramus region of the mandible or maxilla. "Moreover, the expressions of WT1 has also been reported as a significant oncogene to the pathogenesis in various histological type of ameloblastoma." (PMID 35243014, 2022).
amenorrhea (1 paper, 2010). The absence of menses in a woman who has achieved reproductive age. "Among the genetic causes of low-testosterone primary amenorrhea due to 46,XY DSD, SRY gene is reported to be frequently involved, but other genes, such as SF1 and WT1, have never been studied for their prevalence." (PMID 20302644, 2010).
amyloidosis (1 paper, 2019). A disorder characterized by the localized or diffuse accumulation of amyloid protein in various anatomic sites. "Given the sentence, "Hsf-1 affects podocyte markers NPHS1, NPHS2 and WT1 in a transgenic mouse model of TTRVal30Met-related amyloidosis," three entity relations, with relation type and biological context, were extracted by the context-based ABC model." (PMID 31017923, 2019).
Anxiety (1 paper, 2019). Intense feelings of nervousness, tension, or panic often arise in response to interpersonal stresses. "Particularly important for pathologies in the area of trauma and anxiety was the observation that WT1-depleted mice trained in CFC show decreased extinction and an increased anxiety response, as measured by elevated plus maze." (PMID 31434897, 2019).
astrocytic tumor (1 paper, 2020). A glial tumor of the brain or spinal cord showing astrocytic differentiation. "Associations between WT1 expression level and the prognostic indicators of astrocytic tumors including: age IDH1 status apoptotic (Bcl2 index) and cell proliferation (Ki67 index) markers are further studied." (PMID 32856872, 2020). "This study disclosed a significant association between increasing WT1 score and the higher Bcl2 scores and labelling indices in astrocytic tumors (p<0.001)." (PMID 32856872, 2020). "This study elucidates the role of WT1 as a diagnostic and prognostic marker in neuropathology, particularly for astrocytic tumors." (PMID 32856872, 2020). "Thus, establishing the immuno-characteristics of WT1 over various astrocytic tumor grades and linking it to the diagnostic and prognostic biomarkers may need further investigation." (PMID 32856872, 2020). "In this regard, we noticed a concordant increase in WT1 score in relation to cell proliferation in astrocytic tumors." (PMID 32856872, 2020). "Within 57 astrocytic tumors, 33.3% were evaluated as WT1 score +3, 21.1% as score +2, and 35.1% as score +1, while 10.5% of tumors did not express WT1 (score 0)." (PMID 32856872, 2020). "WT1 clone 6F-H2 is a highly accurate positive surrogate marker to differentiate astrocytic tumors notably the challenging grade II diffuse astrocytoma from astrogliosis." (PMID 32856872, 2020). "Positive WT1 differentiated astrocytic tumors (92.6% accuracy) and grade II diffuse astrocytomas (93.5% accuracy) from astrogliosis with high sensitivity, specificity and positive predictive values (p<0.001)." (PMID 32856872, 2020). "IHC was applied to 75 astrocytic lesions (18 astrogliosis and 57 astrocytic tumors) using antibodies directed against WT1 clone 6F-H2, isocitrate dehydrogenase 1(IDH1), Bcl2 and Ki67." (PMID 32856872, 2020). "It has been suggested that WT1 gene plays important roles in the tumorigenesis of astrocytic tumors by promoting their malignant phenotype since high-grade tumors usually express higher levels of WT1 proteins." (PMID 32856872, 2020). "WT1 score significantly associates higher Bcl2 and Ki67 labelling indices, increasing WHO tumor grade and histopathologic type of astrocytic tumors." (PMID 32856872, 2020). "In case of its positivity, WT1 can be used a surrogate marker to differentiate astrocytic tumors notably grade II diffuse astrocytoma from astrogliosis with high accuracy, but is of no value in case of negativity." (PMID 32856872, 2020). "Using IHC, this study investigates the accuracy of WT1 (clone 6F-H2) to differentiate reactive astrogliosis from astrocytic tumors and to characterize different grades and histopathologic types of astrocytic tumors (according to the WHO classification 2016)." (PMID 32856872, 2020). "There was a highly significant statistical difference in WT1 expression (p<0.001) with an overall accuracy of 92.6% in differentiating astrocytic tumors from astrogliosis." (PMID 32856872, 2020). "This tissue microarray (TMA) immunohistochemical (IHC) study elucidates the role of Wilms’ tumor 1 protein (WT1) in diagnosis and prognostication of astrocytic tumors." (PMID 32856872, 2020). "Likewise, Kusum and Ramita (2019), confirmed the significant direct correlation between mitotic index and WT1 score in astrocytic tumors." (PMID 32856872, 2020). "However, some discordance exists in WT1 specificity among earlier studies with a positivity range between 80.9% and 100% in astrocytic tumors." (PMID 32856872, 2020). "This study analyzed comprehensively WT1 expression across astrocytic tumors." (PMID 32856872, 2020). "Of these, is the use of Wilms’ tumor 1 protein (WT1) as a marker to distinguish astrocytic tumors." (PMID 32856872, 2020). "In our samples, WT1 was expressed in 89.5% of astrocytic tumors but not in astrogliosis, conferring a diagnostic accuracy of 92.6% for astrocytic tumors and a 100% PPV." (PMID 32856872, 2020).
astrocytic tumor (continued). "WT1 was expressed by neoplastic astrocytes in 89.5% of astrocytic tumors." (PMID 32856872, 2020). "Yet, recent clinical trials have investigated WT1 as an immunotherapeutic target and supported its prognostic value and its potential utility as a strong immunotherapeutic target in different types of astrocytic tumors in all age groups even in cases with advanced or recurrent disease." (PMID 32856872, 2020). "For both comparisons, WT1 positivity revealed excellent sensitivity (75 and 90% respectively), specificity (100%) and PPV (100%) for astrocytic tumors." (PMID 32856872, 2020). "In agreement with previous studies, we came across 6/57 WT1-negative tumors of different histopathologies, but others didn’t report any negativity in astrocytic tumors." (PMID 32856872, 2020). "Unfortunately, we were unable to compare these findings as WT1 expression data are limited or not available for astrocytic tumors that predominates in children." (PMID 32856872, 2020). "WT1 cytoplasmic expression was detected in 89.5% of astrocytic tumors but not in astrogliosis." (PMID 32856872, 2020).
Atrophy (1 paper, 2011). Any weakening or degeneration, especially through lack of use. "One possibility is that the pancreatic atrophy arises through activation of the sub-population of stellate cells that express Wt1 although further study is required to investigate this hypothesis." (PMID 22216009, 2011).
atypical hemolytic-uremic syndrome (1 paper, 2024). A rare, genetic thrombotic microangiopathy due to dysregulation of the alternative complement pathway and characterized by the triad of hemolytic anemia, thrombocytopenia, and acute renal dysfunction. "Several cases of WT1 gene mutation presenting with atypical hemolytic uremic syndrome (aHUS) have been reported." (PMID 39445256, 2024).
B-cell lymphomas (1 paper, 2021). "In this study, we found five gene fusions (e.g., TCF7L2_WT1) were frequently detected in B-cell lymphomas." (PMID 34926267, 2021). "In this study, we identified novel TCF7L2_WT1 gene fusion as one of the most frequently detected genomic aberrations in B-cell lymphomas." (PMID 34926267, 2021). "We detected five fusion genes in at least two patients with B-cell lymphoma, and among them, TCF7L2_WT1 gene fusion was most frequently detected in 30.4% of patients (24 of 79 cases)." (PMID 34926267, 2021).
bacterial meningitis (1 paper, 2018). Inflammation of the membranes surrounding the brain and spinal cord due to a bacterial infection. "One patient (Pt 005) post allo-SCT on the Montanide arm developed transverse myelitis with evidence of bacterial meningitis following the first monthly booster vaccination, which was deemed not to be related to WT1 vaccination." (PMID 29344432, 2018).
Bochdalek hernia (1 paper, 2016). "Deletion of WT1 in the PHMP/PPFs continuum, i.e. in the G2+ domain, causes a phenotype characterized by defects in the inflow tract of the heart, coronary vessels and, importantly, Bochdalek's hernia, most frequently located in the left side." (PMID 27642710, 2016). "Our findings indicate that WT1 is involved in the generation of the mesenchyme of the ST/PHMP/PPFs continuum through epithelial-mesenchymal transition and they provide a novel perspective on the genesis of the Bochdalek hernia and the evolutionary origin of the diaphragm." (PMID 27642710, 2016).
brain arteriovenous malformation (1 paper, 2021). "In brain arteriovenous malformation, lack of WTAP represses the Wnt/β-catenin pathway by enhancing WT1 activity, resulting in inhibition of angiogenesis of endothelial cells." (PMID 33680959, 2021).
breast adenocarcinoma (1 paper, 2016). "It is therefore tempting to speculate that E2-ERα, in addition to a direct effect on CXXC5 expression, also modulates the transcriptional output of CXXC5 by regulating gene expressions of and interactions with RARα and WT1 in breast tissue and breast adenocarcinomas." (PMID 27886276, 2016).
Burkitt lymphoma (1 paper, 2014). A rare form of malignant mature B-cell non-Hodgkin lymphoma. "In particular, we analyzed the IL-6 receptor genes (IL-6Rα and IL-6ST), PTEN and WT1 expression for their possible relevance to Burkitt lymphoma." (PMID 24731550, 2014).
cardiac arrest (1 paper, 2024). Cessation of breathing and/or cardiac function. "The numbers of WT1+/cTnT+ cells increased in the AVj after cardiac arrest, interpreted as a regenerative response to global hypoxia in the niche region." (PMID 38902373, 2024). "WT1+/cTnT+ showed the highest numbers in the AVj of cardiac arrest group." (PMID 38902373, 2024). "In LV there were no WT1+/cTnT+ cells, except for few cells in tissue from 2 donors in cardiac arrest group." (PMID 38902373, 2024). "Another observation was increased numbers of WT1+/cTnT− cells in LV after cardiac arrest (data not shown) interpreted as an activation of non-myocytes." (PMID 38902373, 2024). "WT1 expression in LV was found in cTnT− cells, between cardiomyocytes, in the cardiac arrest group in tissue from donors; 8, 9, 14, 15 and 16 (data not shown)." (PMID 38902373, 2024).
Cirrhosis (1 paper, 2022). A chronic disorder of the liver in which liver tissue becomes scarred and is partially replaced by regenerative nodules and fibrotic tissue resulting in loss of liver function. "Several oncogenic transcription factors (TFs) inferred with DoRothEA35 including FOS, ETS2, RELB, SOX10, ERG, WT1 and JUND and TFs supporting stemness such as PBPJ and ARID3A were upregulated in cirrhosis patients and correlated with bacterial translocation." (PMID 35803930, 2022).
colorectal adenocarcinoma (1 paper, 2015). The most common type of colorectal carcinoma. "In the present study, WT1 antigens were found to be strongly expressed in colorectal adenocarcinoma tissues in addition to HLA-ABC antigens in both cases, likely representing an advantageous on-target effect of DC vaccination." (PMID 26690485, 2015).
COVID-19 (1 paper, 2021). A disease caused by infection with severe acute respiratory syndrome coronavirus 2. "Immunohistochemical labeling with WT1, a MC marker, showed positivity in spindle-like cells infiltrating the sub-mesothelial stroma of COVID-19 patients." (PMID 34901152, 2021).